IL17A (interleukin 17A)
Diseases named in the same sentence as IL17A in open-access papers (continued):
Sharing a sentence is not in itself a finding about the gene and the disease.
infection (continued). "Besides adaptive immunity evidenced by the increase in milk concentration of IFN-γ and the increase in the IL-17A WBA after infection, the intramammary booster immunization may have induced an innate immune response." (PMID 28611405, 2017). "To determine the relationship between γδ T cells and neutrophils during infection, we depleted γδ T cells from mice infected with S. japonicum from the fifth week after the parasites had laid eggs in the liver to the seventh week, when the level of IL-17A had increased." (PMID 28507072, 2017). "After we confirmed that γδT cells and the Vγ4+γδT subset were the major source of the elevated IL-17A that mediated lung immunopathological injury in severe infection, we further analyzed whether depletion of γδT cells or the Vγ4+γδT subset could alleviate lung injury." (PMID 28912779, 2017). "Notably, in response to infection with a replication-deficient poxvirus modified vaccinia virus Ankara, iBALT development was independent of both IL-17A and another Th17 effector cytokine, IL-17F." (PMID 27752256, 2016). "Hence, IL-17A and IL-17F play distinct roles in extracellular versus intracellular infections." (PMID 27853279, 2016). "In an ex-vivo model of infection with human intestinal biopsies, inoculation with C. jejuni induced IL-17A production which reduced the number of intracellular C. jejuni in the intestinal epithelium, suggesting that this cytokine may contribute to protective immunity against this bacterium." (PMID 26540197, 2015). "Therefore, treatment with anti-IL-17A seems to be favorable in the early phases of exacerbations while blocking IL-1β might be more advantageous during the ongoing infection." (PMID 24918427, 2014). "Importantly, NOD-1/NOD-2 deficiency did not alter IL-17A production during the late “adaptive” phase of infection suggesting that these sensors specifically regulate early CD4+-T-cell-derived IL-17." (PMID 24586147, 2014). "Moreover, potential innate immune cells present at the site of infection may respond to bacterial products by producing IL-17A." (PMID 23378722, 2013). "In order to confirm our observation that γδ+ T cells had increased IL-17A production in mice depleted of neutrophils, we isolated γδ+ T cells from H99γ-infected mice treated with either isotype control antibody or the 1A8 neutrophil-depleting antibody on day 7 post-infection." (PMID 23216912, 2012). "Despite sampling multiple independent gastric mucosal sites to arrive at this conclusion, the apparent persistence of gastric mucosal CD4+IL-17A+ cells in patients from group P might still be due to ongoing infection with HP at localised sites that were missed during endoscopy." (PMID 22761739, 2012). "However, in this mouse model, IL-17A and IL-22 could be detected above uninfected controls only by 6 days after infection." (PMID 22675469, 2012). "Our results indicate that infection with P. aeruginosa may promote the IL-17A and IL-23 expression in CF, since we found that patients chronically infected with P. aeruginosa have higher mRNA expression of both cytokines than patients who were not chronically infected." (PMID 21143945, 2010). "Deficiency of IFN-γ but not IL-17A enhanced susceptibility of control mice to both infections." (PMID 20041174, 2009). "The infection also elicited a dynamic cellular immune response, marked by biphasic IFN-γ production and dose-dependent increases in IL-17A and TNF-α." (PMID 41751072, 2026). "Upon re-infection, healed PTX3-/- mice produced significantly more IL-17A, while levels of IFN-γ, TNF-α, and IL-10 were similar." (PMID 41743710, 2026). "Specifically, CD8αα+hiCD4-TCR1- cells of TCR Cγ−/− chickens showed higher transcription rates of IL-17A, IL-2Rα and IFN-γ compared to CD8αα+hi γδ T cells of wild-type chickens during the early stages of infection." (PMID 40438105, 2025).
infection (continued). "We therefore infected Tbet−/− and Tbet−/−Il17a−/− (Il17aicre/icre referred to as Il17a−/−) littermate-controlled mice with Mtb and measured CFU and T cell responses in the lungs after 3 weeks of infection." (PMID 40463021, 2025). "The qPCR analysis revealed significant upregulation of IL-6, IL-17A, IL-22, IFN-β, IFN-γ, and TNF-α in duodenal epithelial cells following IBV CSL strain infection." (PMID 40871421, 2025). "Complementary ELISA data demonstrated a significant augmentation in the secretion of cytokines IFN-γ, IL-4, IL-6, IL-17A, TGF-β, GATA-3, T-bet, IL-10, and TNF-α in the Pm_OMVs-infected group relative to the Pm group at 24 hours post-infection (P < 0.01)." (PMID 41306977, 2025). "Previous work has demonstrated a vital role of IL-17A in clearance of MRSA in skin and soft tissue infections via Th17 cell responses." (PMID 39966757, 2025). "Four weeks post infection with M.tb HN878, we observed a significant increase in circulating IFN-γ, TNF-α, IL-1β, IL-2, IL-6, IL-12p70, IL-17A/F, IL-15, and IL-33 levels in mice immunized with ID93+EmT4TM compared to saline controls." (PMID 40285479, 2025). "The memory γδ T cells protected the animals from secondary infection in a TCR-dependent manner, by clustering with myeloid cells at L. monocytogenes replication foci, producing IL-17A and cooperating with conventional T cells." (PMID 40700036, 2025). "In turn, IL-17A induces CXCL8 and other chemokines to recruit and activate neutrophils at sites of infection." (PMID 39966757, 2025). "We previously reported that the infection induced TNF-α, IL-17A, and IL-1β expression, which potentially activates the NF-κB signaling pathway." (PMID 40127923, 2025). "We examined IFNγ-, IL17A-, and IL17F-producing T cell subsets, including γδ+, CD4+, and CD8+ T cells, after 14-days post-infection." (PMID 39475280, 2024). "Infection with T. gondii increased the production of all other cytokines (IL-6, IFN-γ, TNF, IL-10, and IL-17A) in all experimental groups." (PMID 39417497, 2024). "In cases of infection, such as with the influenza A virus or the Francisella tularensis bacterium, they expand rapidly and secrete high amounts of IFN-γ and IL-17A." (PMID 39456150, 2024). "Transient higher levels of IL-17A/F and TNF-α were observed at 30 min post infection in the ΔlytS mutant group, but at 24 and 32 hours post infection, levels of both cytokines were found to be significantly lower compared to the WT-infected animals." (PMID 39400158, 2024). "Before infection, the total cell number and percentage of IL-17A+ CD4+ T cells (Th17) and IFN-γ+ IL-17A+ T cells (IFN-γ+ Th17) in cLP were significantly lower in water-restricted mice than in control mice." (PMID 38799550, 2024). "It is noteworthy that the concentrations of IL-9 and IL-17a increased in both IFNAR−/−-BS and C57BL/6J-BS following VSV, NiV and EBOV infections compared to those following mock infection." (PMID 39466030, 2024). "Later after infection (day 10), FITC-dextran levels in baso IL-4/IL-13 (−) mice were negatively correlated with IL-17A, which was the center of a larger network of positively correlated type 1 plasma cytokines." (PMID 38780542, 2024). "Immunohistochemistry revealed altered levels of IL20, IL17A, IL4, and psoriasin, which are involved in infection." (PMID 39337422, 2024). "Prior to infection, T cell responses measured as IFN-γ and IL-17A and CTH522 specific antibody responses in both blood and vaginal secretions were determined." (PMID 38396019, 2024). "Antibodies (IgA and IgG), effector immune cells (CD4+ T cells, macrophages, and neutrophils) and cytokines (including IL-17A and IFN-ɣ) have been shown to play critical roles in regulating immune responses to S. pyogenes at the site of infection." (PMID 38576622, 2024). "IL-17A promotes CXCL5, which has a similar effect to CXCL6, and attracts neutrophils, eosinophils, and T cells to the site of infection, enhancing the local immune response." (PMID 38474048, 2024).
infection (continued). "IL-17A, IL-22, and IFN-γ are tissue-signalling cytokines that play important roles in inflammation and infection." (PMID 39695888, 2024). "The concentrations of mediators including IL-17a, IFN-γ, IL-1α and IL-10 were significantly higher in infected IFNAR−/−-BS compared to mock infections." (PMID 39466030, 2024). "Consistently, 2 weeks post-infection, the mock-vaccinated group showed equal or superior results to other groups, in terms of IFN-gamma and IL-17a." (PMID 38276680, 2024). "During PKDL, there is an increase in the production of Th1-cell-specific cytokines, namely IFN-γ, TNF-α and IL-12, as well as IL-17A, IL17F and IL22 specific to Th17 cells show a protective role during infection." (PMID 39587036, 2024). "Further, analysis of cytokine production revealed similarly upregulated CD4+IL-17A+, CD4+IFNγ+, and CD4+IL-22+ T cells in the colons of RORγtK256R/K256R and WT mice after infection." (PMID 39504243, 2024). "Depletion of CD4+ Th cells from PBMCs isolated on day 7 after infection substantially reduced IL-17A production in response to stimulation with CS6 and CS5, supporting that the observed IL-17A responses to CFs were derived from CD4+ Th cells." (PMID 37809062, 2023). "The colonic cytokine contents were analyzed, and it was detected that CR infection promoted the pro-inflammatory factors IL-1β, TNF-α, IL-6, and IL-17A (p < 0.01), as well as the anti-inflammatory factors IL-4 (p > 0.05) and IL-10 (p < 0.01)." (PMID 37111225, 2023). "More importantly, both SARS-CoV-2 and pCoV-GD01 infection induced the production of cytokines such as IFN-gamma, IL-12p70, IL-13, IL-2, IL-5, TNF-alpha, IL-17A, IP-10, MCP-3, MIP-1beta, MIP-2, Exotaxin, IL-15/15R, IL-28, IL-3, G-CSF, IL-1alpha and ENA-78." (PMID 37330497, 2023). "Significant induction of type 17-related cytokines, including IL-17a and IL-22, was observed in lung tissue homogenates and/or bronchoalveolar lavage (BAL) of mice between days 5–11 after PR8 infection." (PMID 37726288, 2023). "In this study, we observed that mice treated with HK-fbp1 at day 3 after infection exhibited high Th1 and Th17 protective responses, evident by increased production of IFN-γ and IL-17A cytokines and reduced Th2 cytokines (IL-13)." (PMID 36719231, 2023). "Lower age, PCR CT, IL-6, IL-8, and IL-17A and higher IL-16, EGF, and CCL-5 appeared to provide the best univariate class separation for recurrent infection (versus recurrence-free survival and death)." (PMID 36975808, 2023). "Early infection cytokines and chemokines consist of proinflammatory IL-6, CXCL1, CCL2, CCL3, G-CSF, GM-CSF, and IL-1β; later on, IL-17A, IL-17F, and CCL4 levels increase." (PMID 36978425, 2023). "In MDV infection, we observed an increase in both IL-17A and IFN-γ during the early stage of infection." (PMID 37631976, 2023). "In the small intestine, among six types of γδ T cells, IL-17A-producing Vγ4 and Vγ6 T cell receptor (TCR) γδ T cells were selectively expanded following infection." (PMID 37939119, 2023). "Some other interesting, enriched pathways identified for 3 hours post-infection included Sertoli and germ cell-Sertoli cell junction signaling, CD27 signaling in lymphocytes, IL-17A signaling in fibroblasts, and 5′-AMP-activated protein kinase signaling." (PMID 37615437, 2023). "We analyzed IL-17A expressing CD4+ T cells in the lung at 6 and 21 days after infection by intracellular cytokine staining following in vitro stimulation with heat-killed P1121, T4 and a gram-negative bacterium, H. influenzae strain NT127." (PMID 37222516, 2023). "Th cells play major roles in controlling anti-infection responses of phagocytic effector cells: Th1 cells produce IFN-γ, which activates macrophages and cytotoxic T cells, while Th17 cells produce IL-17A, which recruits neutrophils to infection sites." (PMID 36723073, 2023).
infection (continued). "We recently described a role for IL-17A, through suppression of interferon (IFN)-γ, as an important inducer of type 2 responses during infection with the lung-migrating rodent nematode Nippostrongylus brasiliensis." (PMID 37783278, 2023). "In a related chronic biofilm mesh infection mouse model, CXCL2 and CXCL9 persisted, but the other cytokines were replaced by IL-1A and IL-17A, suggesting an early Th1 and Th17 response." (PMID 36978425, 2023). "Filaggrin, HIF-1α, VEGF, RANTES/CCL5, IL-17A, IL-1β, MIP-1α and MIP-1β/CCL5 levels were higher during and after infection." (PMID 36482106, 2022). "In agreement with the previous study, resident MAIT cells in the lung were IL-17A-producing cells, suggesting that functional differentiation and/or expansion of Th1-type MAIT cells occurs after infection with the avirulent Francisella strain." (PMID 35667686, 2022). "However, after in vitro stimulation with Leishmania, VL-AT samples presented an increased ability to produce IL-17A in response to the infection than VL-BT samples, in line with the hypothesis that IL-17A+ MAIT cells are preferentially selected after drug treatment." (PMID 36189274, 2022). "After experimental infection with Mycobacterium bovis bacille Calmette-Guérin (BCG) as well as Mtb, IL-17A contributed to the formation and maturation of lung granulomas." (PMID 36139450, 2022). "Although NK cells and neutrophils were rapidly increased in the lungs during the first 2 weeks of infection, CD3+ cells, especially RORγt+ cells, represented the major source of IL-17A." (PMID 35363832, 2022). "ATRA boosted the IL‐17A effects and further increased HIV trans‐infection with coincidental reduction of IL‐32 expression; T0070907 exhibited opposite effects." (PMID 35916394, 2022). "Whereas after infection with <100 CFU Mtb, wildtype and IL-17A−/− mice had to be euthanized with a similar kinetic, infection with an elevated dose of Mtb resulted in a significantly diminished survival time in the mutant mice." (PMID 36139450, 2022). "Levels of IL-17A and TNFSF14 are enhanced early after infection and gradually increase until late time points." (PMID 35479098, 2022). "During a bacterial pneumonia infection, IL-17A, produced by CD4+ and CD8+ T cells, is important for the production of G-CSF and MIP-2, as well as recruiting neutrophils to the site of infection to aid host defense." (PMID 36140808, 2022). "After in vitro stimulation with Leishmania, MAIT cells from VL-AT children produced exclusively IL-17A, suggesting that MAIT cells expressing IL-17A were selectively preserved after infection resolution." (PMID 36189274, 2022). "During primary infection, neutrophils were able to boost IL-2 and IFN-γ production by CD4+ and CD8+ T cells and IL-17A production by CD4+ T cells." (PMID 35185880, 2022). "At week 6 post-infection, percentages of KLRG1+ T cells were decreased in vaccinated C57BL/6, IL-23p19−/−, and IL-17A−/− mice to a similar extent." (PMID 34351501, 2021). "Here, it was shown that infection with Dengue virus 2 (DENV2) in mice resulted in an upregulated expression of IL-22 and IL-17A." (PMID 33851257, 2021). "In infection with the H1N1 influenza virus, the same research group observed that infected il17a-/- mice had a lower survival rate, greater tissue damage and greater viral load in lung tissue than wild-type mice." (PMID 34064728, 2021). "Other possible facilitators of IL-17A expression include IL-6, as it is increased during MHV68 infection, or IL-21, as IL-21 signaling is required for efficient establishment of MHV68 latency and germinal center response in infected mice." (PMID 33824206, 2021). "Suggesting low systemic response, the blood of mice trained 9 weeks contained lower levels of a broad range of cytokines (IL-1β, IL-6, IL-10, IL-12p40, IL-17A, IL-18, IFNγ, TNF, CCL2 and CXCL5) 2 days after infection with L. monocytogenes." (PMID 34603295, 2021).
infection (continued). "RV-C15 infection of naïve mice increased BAL monocytes, neutrophils, eosinophils and lymphocytes, while inducing mRNA expression of IFN-γ, CXCL10, IL-17A, IL-13 and IL-5." (PMID 33968043, 2021). "Additionally, in this context, another study showed that IL-17A-induced protection is important with regard to secondary HSV-2 infection, since il17a-/- mice that were re-exposed to the virus were more susceptible to virus spread, morbidity and mortality than were knockout mice in primary infection." (PMID 34064728, 2021). "After 1 day of infection, the oral tissues of the gefitinib-treated mice contained significantly less CXCL1/KC, CCL20, IL-1α, IL-1β, IL-17A, and the host defense peptide S100A8 than control mice." (PMID 33471869, 2021). "Among serum molecules identified in non-neurological and neurological diseases in the acute phase of the infection, 12 (IL-1β, IL-6, TNF, IL-2, IL-7, IL-17A, IL-15, IFN-α, IL-5, IL-13, IL10, and GM-CSF) were shared by both networks." (PMID 33776990, 2021). "Alternative potential biomarkers of bTB disease progression include IL-17A, also of the Th17 subset, and CXCL9 due to the observed increase as infection progresses with additional correlations to lesion severity." (PMID 33746980, 2021). "Strikingly, infection with S. tm. induced in eSPF+SFB mice compared to SPF mice significantly increases the frequencies and numbers of IL-17A-IL-22+ and IL-17A+IL-22+ CD4+ T cells specifically in the cecal LPLs." (PMID 34566952, 2021). "After RV1b infection of PBMC the independency between the IL-17A and IFN-β pathway was shown, since IFN-β was increased, while IL-17A and OAS1 were reduced." (PMID 34691038, 2021). "Upon infection, it was observed that IL-17A was induced at both the mRNA and the protein level, as well as in adaptive immune cells, suggesting a potential role for TH17 responses during infection." (PMID 34240122, 2021). "In the present study, quantitative real-time RT-PCR analysis revealed that after infection with Mtb, the expression of Il17f was increased in H1-DDA/TDB-vaccinated IL-17A−/− mice in comparison to vaccinated C57BL/6 mice." (PMID 34351501, 2021). "CXCL2 (MIP‐2) and CXCL1 (KC), which are responsible for the infiltration of neutrophils and monocytes, were suppressed at the beginning of infection (6 h), whereas inhibition of CCL2 (MCP‐1), TNF‐α, IL‐6, IL‐1β and IL‐17A appeared after 24 h." (PMID 33014369, 2020). "CA infected control mice specifically expressed IL-17A (y-axis) and very little IFN-γ (x- axis) in response to the infection." (PMID 33240286, 2020). "Examining IL-17A and IFN-γ in Foxp3-negative effector CD4+ T cells on day 3 after re-infection, we found that both sham groups had negligible but comparable levels of cytokine producers." (PMID 33240286, 2020). "Expression of IFNG, IL17A, IL12B, and IL27 was analyzed with PBMCs and PP cells isolated at 28 days post-infection and re-stimulated with individual recombinant MAP proteins." (PMID 33329565, 2020). "To evaluate variations in immune response according to KoRV subtype infection status, we measured expression levels for CD4, CD8b, IL-6, IL-10, and IL-17A in RNA isolated from unstimulated koala PBMCs." (PMID 33316950, 2020). "In the spleens of IM-immunized mice, the frequencies of CD4+ T cells expressing IL-17A, IFN-γ, IL-10 and TNF-α were found similar when compared to controls, both before and after infection." (PMID 32040500, 2020). "Infection with BCG was shown to exert a detrimental effect primarily upon epithelial cells, with corresponding increases in IL8, TNFα, IL22 and IL17a cytokine release, quantified by ELISA." (PMID 33116165, 2020). "Higher production of IL-17A, IFN-γ, IL-10, IP-10, GM-CSF, sFasL, Granzyme A, Granzyme B, Granulysin, and Perforin following infection positively correlated with HIV replication." (PMID 33214610, 2020).